TRIM49B (tripartite motif containing 49B)
Tractability: No criterion of Open Targets' tractability assessment is met for any kind of drug.
Gene: Protein-coding gene on chromosome 11 (49,027,501 to 49,038,451, forward strand). Ensembl gene ENSG00000182053.
Gene Ontology:
Molecular function: ubiquitin protein ligase activity; zinc ion binding
Biological process: innate immune response; regulation of gene expression
Cellular component: cytoplasm
Genetic constraint (gnomAD): Loss-of-function variants: 18 observed, 28.25 expected, observed/expected ratio (o/e) 0.64, 90% interval 0.44 to 0.94. The upper end of that interval is the gene's LOEUF score, 0.94, which puts it in group 4 of 6, group 1 being the genes least tolerant of losing a copy. Missense variants: 490 observed, 524.67 expected, observed/expected ratio (o/e) 0.93, 90% interval 0.87 to 1.01. Synonymous variants: 195 observed, 174.01 expected, observed/expected ratio (o/e) 1.12, 90% interval 1 to 1.26.
Homologues: Orthologues: chimpanzee TRIM49B (88% identical). Paralogues in human: TRIM49 (95% identical), TRIM49C (95% identical), TRIM49D1 (85% identical), TRIM49D2 (85% identical), TRIM51 (76% identical), TRIM51G (72% identical), TRIM43 (52% identical), TRIM43B (51% identical), TRIM64 (46% identical), TRIM64B (46% identical), TRIM64C (45% identical), TRIM77 (43% identical), and 68 more.
Diseases named in the same sentence as TRIM49B in open-access papers:
TRIM49B is named in the same sentence as 4 diseases in open-access papers, as found by Europe PMC text mining. Sharing a sentence is not in itself a finding about the gene and the disease.
TRIM49B shares sentences with these, for which no sentence is quoted: infection (1 paper); major depressive disorder (1); malignant brain tumors (1); tumor (1).